MIR4509-3 (microRNA 4509-3)
Synonyms: hsa-mir-4509-3
Gene: MicroRNA gene on chromosome 15 (28,490,752 to 28,490,845, reverse strand). Ensembl gene ENSG00000263964.
Homologues: Paralogues in human: MIR4509-1 (100% identical), MIR4509-2 (100% identical).